ATG9A (autophagy related 9A)
Description:
Phospholipid scramblase involved in autophagy by mediating autophagosomal membrane expansion. Cycles between the preautophagosomal structure/phagophore assembly site (PAS) and the cytoplasmic vesicle pool and supplies membrane for the growing autophagosome. Lipid scramblase activity plays a key role in preautophagosomal structure/phagophore assembly by distributing the phospholipids that arrive through ATG2 (ATG2A or ATG2B) from the cytoplasmic to the luminal leaflet of the bilayer, thereby driving autophagosomal membrane expansion. Also required to supply phosphatidylinositol 4-phosphate to the autophagosome initiation site by recruiting the phosphatidylinositol 4-kinase beta (PI4KB) in a process dependent on ARFIP2, but not ARFIP1. In addition to autophagy, also plays a role in necrotic cell death (By similarity).
Synonyms: APG9L1; FLJ22169; MGD3208; mATG9
Tractability: Small molecule: a structure with a bound ligand is known. Antibody: UniProt predicts a signal peptide or a membrane-spanning region. PROTAC: UniProt records ubiquitination sites on it; ubiquitination databases record sites on it; its protein half-life has been measured.
Gene: Protein-coding gene on chromosome 2 (219,219,380 to 219,229,717, reverse strand). Ensembl gene ENSG00000198925.
Subcellular location: Preautophagosomal structure membrane; Cytoplasmic vesicle, autophagosome membrane; Golgi apparatus, trans-Golgi network membrane; Late endosome membrane; Recycling endosome membrane; Endoplasmic reticulum membrane; Mitochondrion membrane
Subcellular location (Human Protein Atlas): Vesicles
Pathways (Reactome):
Autophagy: Macroautophagy; PINK1-PRKN Mediated Mitophagy
Gene Ontology:
Molecular function: phospholipid scramblase activity; protein binding
Biological process: autophagosome assembly; bone morphogenesis; mitophagy; piecemeal microautophagy of the nucleus; programmed necrotic cell death; protein localization to phagophore assembly site; reticulophagy; autophagy; plasma membrane phospholipid scrambling
Cellular component: autophagosome membrane; endoplasmic reticulum membrane; endosome; Golgi apparatus; Golgi membrane; late endosome; late endosome membrane; membrane; mitochondrion; phagophore assembly site; phagophore assembly site membrane; recycling endosome; recycling endosome membrane; trans-Golgi network; autophagosome; cytoplasm; mitochondrial membrane; synaptic membrane
Genetic constraint (gnomAD): Loss-of-function variants: 21 observed, 90.75 expected, observed/expected ratio (o/e) 0.23, 90% interval 0.16 to 0.33. The upper end of that interval is the gene's LOEUF score, 0.33, which puts it in group 1 of 6, group 1 being the genes least tolerant of losing a copy. Missense variants: 836 observed, 1,146.8 expected, observed/expected ratio (o/e) 0.73, 90% interval 0.69 to 0.77. Synonymous variants: 422 observed, 457.82 expected, observed/expected ratio (o/e) 0.92, 90% interval 0.85 to 1.
Homologues: Orthologues: chimpanzee ATG9A (99% identical), rabbit ATG9A (99% identical), pig ATG9A (98% identical), rat Atg9a (98% identical), mouse Atg9a (98% identical), guinea pig ATG9A (96% identical), dog ATG9A (92% identical), zebrafish atg9a (73% identical), tropical clawed frog atg9a (70% identical), Drosophila melanogaster Atg9 (38% identical), Caenorhabditis elegans atg-9 (34% identical). Paralogues in human: ATG9B (44% identical).
Diseases named in the same sentence as ATG9A in open-access papers:
ATG9A is named in the same sentence as 75 diseases in open-access papers, as found by Europe PMC text mining. Sharing a sentence is not in itself a finding about the gene and the disease. The quoted sentences say what the papers report.
breast carcinoma (6 papers, 2016 to 2026). "Our analysis showed that high ATG9A levels were associated with longer RFS in all breast cancer patients and interestingly, the same trend was also observed in patients with Her2 amplification." (PMID 27050377, 2016). "However, the function of ATG9A and its associated signaling in trastuzumab sensitivity in breast cancer were unknown." (PMID 27050377, 2016). "It has been reported that ATG1/ULK1 acts as an upstream signal for actomyosin activation and ATG9A trafficking during the process of autophagy in Drosophila cells and Human breast cancer cells." (PMID 34131310, 2021). "In our study, we observed an increase in ATG9A mRNA expression in TNBC samples from our breast cancer cohort." (PMID 30563263, 2018). "The correlations of ATG9A expression levels with relapse free survival (RFS) in all breast cancer patients as well as in the subgroup of Her2 amplified breast cancer were assessed." (PMID 27050377, 2016). "Collectively, our results suggest a role for ATG9A in Her2 endosomal/lysosome target degradation via c-Cbl K63 polyUb, which might be a unique signature in trastuzumab resistant breast cancer cells." (PMID 27050377, 2016). "However, when the authors analyzed ATG9A mRNA levels and correlated them with clinicopathological characteristics (ER, PR, or HER2 status), they only demonstrated a significantly lower ATG9A expression in the HER2+ subtype of breast cancers." (PMID 30563263, 2018). "However, in breast cancer, study showed that downregulation of ATG9B but not its orthologue ATG9A could accelerate breast cancer progression, signifying that ATG9A and ATG9B have different biological function in cancer." (PMID 34131310, 2021).
Parkinson disease (5 papers, 2018 to 2024). A progressive degenerative disorder of the central nervous system characterized by loss of dopamine producing neurons in the substantia nigra and the presence of Lewy bodies in the substantia nigra and locus coeruleus. "Interestingly, altered ATG9A localisation can be caused by the Parkinson’s disease–associated VPS35 mutation D620N, which also impairs autophagy." (PMID 36446521, 2023). "Rubinzstein and colleagues have reported an accumulation of ATG9a at the TGN during autophagy upon suppression of endogenous VPS35 followed by re‐expression of the Parkinson‐related mutant VPS35‐D620N." (PMID 29158324, 2018). "Since locomotor impairment is a common phenotype of neurodegenerative disorders such as Parkinson disease, the function of ATG9A in neurons might be related to the progression of neurodegeneration." (PMID 39099167, 2024).
cardiac hypertrophy (4 papers, 2017 to 2025). "Research has shown that inhibition of Atg9a, and thus also of autophagy, was suppressed, which could significantly reverse angiotensin II-induced myocardial hypertrophy." (PMID 37723445, 2023).
hereditary spastic paraplegia (4 papers, 2023 to 2024). Hereditary spastic paraplegias (HSP) comprise a genetically and clinically heterogeneous group of neurodegenerative disorders characterized by progressive spasticity and hyperreflexia of the lower limbs. "Thus, the adaptor protein AP-4, mediating the ATG9A export from the trans-Golgi network to the phagophore assembly site, is mutated in Hereditary Spastic Paraplegia (HSP), an upper motor neuron disease." (PMID 38201307, 2024).
cervical carcinoma (3 papers, 2019 to 2023). A carcinoma arising from either the exocervical squamous epithelium or the endocervical glandular epithelium. "To investigate a possible role for ATG9A in virus replication, we knocked out ATG9A in HeLa cervical carcinoma and Jurkat T cells, and analyzed virus release and infectivity." (PMID 31269971, 2019). "We found that Nef and ATG9A did not alter each other’s localization or levels in HeLa cervical carcinoma or Jurkat T cells." (PMID 31269971, 2019).
glioblastoma (3 papers, 2018 to 2021). The most malignant astrocytic tumor (WHO grade IV). "They found that ATG9A was commonly upregulated in glioblastoma (GBM) in conditions of both short-term and long-term hypoxia." (PMID 31803616, 2019). "A third study described that ATG9A was induced in response to hypoxia in glioblastoma (GBM) and that ATG9A depletion led to decreased in vitro proliferation as well as delayed in vivo tumor growth." (PMID 30563263, 2018).
neuroblastoma (3 papers, 2018 to 2025). Neuroblastoma (NB) is the most common solid, extracranial childhood tumor. "Given the relevance of lysosomal integrity in neurons, we tested ATG9A lysosomal colocalization in a more physiological model using SH-SY5Y neuroblastoma cells differentiated into neuron-like cells prior to LLOMe treatment." (PMID 40460835, 2025). "ATG9A localisation depends on AP-4 not only in HeLa cells, but also in neuroblastoma-derived SH-SY5Y cells and in fibroblasts from AP-4-deficient patients, suggesting that trafficking of ATG9A from the TGN is a ubiquitous function of AP-4." (PMID 30262884, 2018). "To determine whether ATG9A is similarly affected by loss of AP-4 in a cell line more relevant to the neuronal phenotypes of AP-4 deficiency, we used CRISPR/Cas9-mediated gene editing to deplete AP4B1 or AP4E1 in mixed populations of SH-SY5Y neuroblastoma cells." (PMID 30262884, 2018).
ovarian carcinoma (3 papers, 2016 to 2025). A malignant neoplasm originating from the surface ovarian epithelium. "TCGA analysis shows lower ATG9A mRNA is associated with better survival on the pan-cancer level, as well as in a number of individual cancers such as ovarian cancer." (PMID 40595560, 2025). "ATG9A has been shown to be upregulated in human oral squamous cell carcinoma, ovarian cancer, and TBNC, and is associated with overall survival and progression-free survival." (PMID 37782756, 2023). "Our study reveals that ATG9A plays a multifaceted role in regulating ovarian cancer cell responses to macrophage-induced cytotoxicity through mechanisms involving plasma membrane repair, lipid metabolism, and inflammatory signaling." (PMID 40595560, 2025). "Among the ten top hits, ATG9A had the highest pan-cancer Z-score and the second highest Z-score in ovarian cancer, strongly linking it to poor prognosis." (PMID 40595560, 2025). "Inconsistently, the study of Dai and colleagues described an up-regulation of ATG9A expression in ovarian carcinomas." (PMID 27825125, 2016). "Transfection of miR-29b inhibits ovarian cancer development by suppressing ATG9A mRNA expression directly." (PMID 27825125, 2016). "Similarly, ATG9A, a downstream target gene of miR-29b, was significantly elevated in ovarian cancer, and ATG9A protein expression level was negatively correlated with overall survival and progression-free survival." (PMID 37782756, 2023). "Moreover, transfection of miR-29b which was tumor suppressor could inhibit ATG9A mRNA expression directly in ovarian cancer." (PMID 27825125, 2016). "Our studies did not use syngeneic tumors, primary human PDX models, or non-ovarian cancer models, but future studies in these models would help elucidate the impact of other immune cells in ATG9A deficient tumors, cancer heterogeneity, and ATG9A’s function in other tumor types." (PMID 40595560, 2025). "ATG9A plays an important role in regulating tumour volume, regional lymph node involvement, and advanced stage in oral squamous cell carcinoma, TNBC, and ovarian cancer." (PMID 37782756, 2023). "Elevated ATG9A is negative related with overall survival and progression-free survival in ovarian cancer." (PMID 27825125, 2016).
pancreatic cancer (3 papers, 2016 to 2018). "In contrast, knockdown of ATG9A in pancreatic cancer cells induced an accumulation of the LC3B-II form." (PMID 30563263, 2018). "In addition, microRNAs targeting the ATG9A mRNA inhibit autophagy and constitute potential therapeutic tools in pancreatic cancer, acute kidney injury, and cardiac hypertrophy." (PMID 29568063, 2018). "Consistently, we observed higher ATG9A and TFEB expression in pancreatic cancer cells that have low miR-29a expression (Panc-1 and MIA PaCa-2), compared to normal pancreatic epithelial cell line (HPNE) and cancer cell line with high miR-29 expression (AsPC-1)." (PMID 27626694, 2016). "We found downregulation of miR-29 in a range of pancreatic cancer cell lines, and restored expression of miR-29a blocked autophagy flux by inhibiting expression of key autophagy proteins, TFEB and ATG9A." (PMID 27626694, 2016). "In our western blot analysis, overexpression of miR-29a in pancreatic cancer cells resulted in a marked downregulation of both TFEB and ATG9A expression." (PMID 27626694, 2016).
AP-4 deficiency syndrome (2 papers, 2018 to 2024). A genetic disorder associated with variation(s) in the AP4 genes: AP4B1, AP4E1, AP4M1, and AP4S1.
colon cancer (2 papers, 2016 to 2025). "The knockout of autophagy-related genes RB1CC1, ATG9A, and ATG12 significantly increased tumor cell susceptibility to T-cell killing in breast and colon cancers and enhanced the anti-cancer effect of PD-1 and CTLA-4 checkpoint inhibitors." (PMID 40641524, 2025). "In breast and colon cancers, the sensitivity of tumor cells to T-cell killing was significantly enhanced by knocking out autophagy-related genes RB1CC1 (RB1 inducible coiled-coil 1), ATG9A, and ATG12." (PMID 40641524, 2025). "However, BIX01294 induced changes could be cell-type specific, as in human colon cancer HCT116 cells the expression of LC3B, ATG9A, ATG4A, but not ATG4B/C, ATG7, BECN1, WIPI1 was increased after BIX01294 treatment." (PMID 27934912, 2016).
colorectal cancer (2 papers, 2022 to 2024). A primary or metastatic malignant neoplasm that affects the colon or rectum. "Conversely, silencing NEAT1 reduces autophagy by influencing ATG9A and ATG4B, which increases sensitivity to 5-fluorouracil in colorectal cancer." (PMID 39715205, 2024). "Consistently, NEAT1 also induces autophagy by targeting miR-34a and miR-204 as a competing endogenous RNA (ceRNA) in colorectal cancer and HCC, respectively, resulting in the upregulation of autophagy-related proteins ATG9A, ATG4A, and ATG3." (PMID 36430876, 2022).
glioma (2 papers, 2019 to 2022). A benign or malignant brain and spinal cord tumor that arises from glial cells (astrocytes, oligodendrocytes, ependymal cells). "For the glioma TCGA cohort, the risk score was calculated as follows: risk score = (0.6457 × PGAM5 expression) + (0.8062 × SQSTM1 expression) + (−0.4834 × ATG9A expression) + (−0.6285 × GABARAPL1 expression)." (PMID 36292980, 2022).
liver fibrosis (2 papers, 2024). "Additionally, NEAT1 upregulates ATG9A, contributing to IGFBPrP1-induced autophagy and activation in hepatic stellate cells during liver fibrosis." (PMID 39715205, 2024).
oral squamous cell carcinoma (2 papers, 2018 to 2023). "ATG9A dysregulation has already been linked to cancer, since ATG9A protein overexpression has been associated with poor survival in patients with oral squamous cell carcinoma, whereas ATG9A inhibition was associated to the apparition of Trastuzumab resistance in HER2+ BC cells." (PMID 30563263, 2018). "A previous study has found that overexpression of ATG9A protein contributed to neoplasm volume enlargement and lymph node metastasis in oral squamous cell carcinoma." (PMID 37782756, 2023).
Salmonella Infections (2 papers, 2019 to 2025). Infections with bacteria of the genus SALMONELLA. "Further, CrARFIP2KO cells showed a reduced number of LGALS3 spots during Salmonella infection, together with an increased association of ATG9A and PI4K2A with the bacteria." (PMID 40460835, 2025). "ATG9A is required to suppress Salmonella infection, as it drives the formation of the autophagosome surrounding invading Salmonella." (PMID 30917996, 2019).
actinic keratosis (1 paper, 2022). A precancerous lesion of the skin composed of atypical keratinocytes. "In addition, the results of quantitative real-time PCR and immunohistochemistry analysis demonstrated the abnormal expression of TIMP3 and ATG9A in actinic keratosis and cutaneous squamous cell carcinoma skin tissues." (PMID 35450405, 2022).
acute kidney tubular necrosis (1 paper, 2025). Acute renal failure caused by the cell death of the renal tubules. "Additionally, increased levels of both p-AMPK and ATG9A were observed in a study on acute kidney tubular necrosis." (PMID 40067389, 2025).
adrenocortical carcinoma (1 paper, 2022). "The risk score for the adrenocortical carcinoma TCGA cohort was calculated as follows: risk score = (−0.622 × SQSTM1 expression) + (0.8342 × ATG9A expression)." (PMID 36292980, 2022).
Ataxia (1 paper, 2018). Ataxia refers to impaired coordination of voluntary muscle movement. "Neuronal deficiency of Atg9a in mice leads to progressive axonal degeneration, ataxia and convulsions." (PMID 30262884, 2018).
breast tumors (1 paper, 2025). "On the contrary to our findings, in a previous study on breast tumors, promoter hypermethylation of ATG9A, ATG9B, ATG2B, and ATG4D genes was linked to reduced gene expression." (PMID 40949798, 2025).
Cerebral ischemia (1 paper, 2020). Restriction of arterial blood supply to the brain associated with insufficient oxygenation to support the metabolic requirements of the tissue. "The aim of this study is to explore the function of NMMHC IIA in cerebral ischemia-induced neuronal autophagy and the underlying mechanism related to autophagy-related gene 9A (ATG9A) trafficking." (PMID 32513915, 2020). "The NMMHC IIA–actin interaction promotes ATG9A trafficking and autophagy formation in cerebral ischemia/reperfusion." (PMID 32513915, 2020). "In conclusion, we show that autophagy induction by NMMHC IIA is involved in cerebral ischemia/reperfusion-induced neuronal cell death, which could be attributed to interactions with F-actin and transport ATG9A from TGN." (PMID 32513915, 2020).
Chlamydia infection (1 paper, 2023). "To elucidate the importance of ATG9A in Chlamydia infection, we employed an ATG9A-KO HeLa cell line, in which autophagic flux was blocked." (PMID 37707289, 2023). "Because the defect of Atg9A reportedly upregulates STING-mediated type I IFN response in MEF, the same response may have occurred in ATG9A-KO HeLa cells, preventing Chlamydia infection." (PMID 37707289, 2023). "On the other hand, STING/pTBK1-double positive puncta were distinctly observed in ATG9A-KO HeLa cells regardless of Chlamydia infection." (PMID 37707289, 2023).
colitis (1 paper, 2021). Inflammation of the colon. "ATG9A decreases in DSS-induced colitis, and the overexpression of ATG9A improves autophagy induced by rapamycin." (PMID 34588980, 2021).
Diplopia (1 paper, 2023). Diplopia is a condition in which a single object is perceived as two images, it is also known as double vision. "Recently, biallelic variants in ATG9A were reported in immune dysregulation with diplopia and inflammatory lesions in brain MRI studies after EBV infection." (PMID 37895210, 2023).
dysplasia (1 paper, 2016). A usually neoplastic transformation of the cell, associated with altered architectural tissue patterns. "While Atg9a KO mice did not display obvious skeletal dysplasia, they were significantly smaller than newborn wild-type mice and Atg5 KO mice." (PMID 27811852, 2016).
endometriosis (1 paper, 2021). The growth of functional endometrial tissue in anatomic sites outside the uterine body. "In a mouse model of surgically induced endometriosis, ectopic lesions revealed increased levels of autophagy-related protein 9A (ATG9A), an autophagic protein involved in vesicle formation." (PMID 34064854, 2021).
epidermal disease (1 paper, 2022). A skin disease that involves the epidermis. "Consequently, we evaluated the levels of TIMP3 and ATG9A in UVB exposure-related epidermal diseases, including AK and cSCC." (PMID 35450405, 2022).